ADM (adrenomedullin)
Description:
Adrenomedullin/ADM and proadrenomedullin N-20 terminal peptide/PAMP are peptide hormones that act as potent hypotensive and vasodilatator agents. Numerous actions have been reported most related to the physiologic control of fluid and electrolyte homeostasis. In the kidney, ADM is diuretic and natriuretic, and both ADM and PAMP inhibit aldosterone secretion by direct adrenal actions. In pituitary gland, both peptides at physiologically relevant doses inhibit basal ACTH secretion. Both peptides appear to act in brain and pituitary gland to facilitate the loss of plasma volume, actions which complement their hypotensive effects in blood vessels. [Adrenomedullin]: Peptide hormone that act as potent hypotensive and vasodilatator agents. ADM function is mediated by the CALCRL-RAMP2 and CALCRL-RAMP3 receptor complexes with ADM showing the highest potency for the CALCRL-RAMP2 complex. [Proadrenomedullin N-20 terminal peptide]: Peptide hormone that act as potent hypotensive and vasodilatator agents by inhibiting catecholamine secretion from sympathetic nerve endings and adrenal chromaffin cells. Acts as a ligand for MRGPRX2 receptor in mast cells. [Proadrenomedullin 9-20 terminal peptide]: Peptide hormone that act as potent hypotensive and vasodilatator agents by inhibiting catecholamine secretion from sympathetic nerve endings and adrenal chromaffin cells. Acts as a ligand for MRGPRX2 receptor in mast cells.
Synonyms: AM; PAMP
Tractability: Small molecule: a structure with a bound ligand is known; a high-quality ligand is known. Antibody: a drug acting on it is in phase 2 or 3 trials; UniProt places it where antibodies can reach, with high confidence; its Gene Ontology location is reachable by antibodies, with high confidence; UniProt predicts a signal peptide or a membrane-spanning region. PROTAC: ubiquitination databases record sites on it.
Target class: Secreted protein
Gene: Protein-coding gene on chromosome 11 (10,303,392 to 10,307,397, forward strand). Ensembl gene ENSG00000148926.
Subcellular location: Secreted
Pathways (Reactome):
Signal Transduction: Calcitonin-like ligand receptors; G alpha (s) signalling events
Cellular responses to stimuli: High laminar flow shear stress activates signaling by PIEZO1 and PECAM1:CDH5:KDR in endothelial cells
Gene Ontology:
Molecular function: adrenomedullin receptor binding; hormone activity; signaling receptor binding; receptor ligand activity
Biological process: adenylate cyclase-activating G protein-coupled receptor signaling pathway; adrenomedullin receptor signaling pathway; G protein-coupled receptor internalization; negative regulation of vasoconstriction; positive regulation of heart rate; receptor internalization; regulation of systemic arterial blood pressure; regulation of urine volume; vasculogenesis; inflammatory response; positive regulation of progesterone biosynthetic process; signal transduction; calcitonin family receptor signaling pathway; negative regulation of vascular permeability; positive regulation of angiogenesis; positive regulation of vasculogenesis; vascular associated smooth muscle cell development
Cellular component: cytoplasm; extracellular region; secretory granule lumen
Genetic constraint (gnomAD): Loss-of-function variants: 2 observed, 10.83 expected, observed/expected ratio (o/e) 0.18, 90% interval 0.074 to 0.58. The upper end of that interval is the gene's LOEUF score, 0.58, which puts it in group 2 of 6, group 1 being the genes least tolerant of losing a copy. Missense variants: 253 observed, 267.86 expected, observed/expected ratio (o/e) 0.94, 90% interval 0.85 to 1.05. Synonymous variants: 107 observed, 115.01 expected, observed/expected ratio (o/e) 0.93, 90% interval 0.79 to 1.09.
Homologues: Orthologues: chimpanzee ADM (100% identical), pig ADM (86% identical), dog ADM (82% identical), macaque ADM (82% identical), rabbit ADM (81% identical), rat Adm (70% identical), mouse Adm (66% identical), guinea pig ADM (64% identical), tropical clawed frog adm (38% identical), zebrafish adma (34% identical), zebrafish admb (24% identical). Paralogues in human: ADM2 (15% identical).
Diseases named in the same sentence as ADM in open-access papers:
ADM is named in the same sentence as 269 diseases in open-access papers, as found by Europe PMC text mining. Sharing a sentence is not in itself a finding about the gene and the disease. The quoted sentences say what the papers report.
Sepsis (109 papers, 2005 to 2026). Sepsis is defined as life-threatening organ dysfunction caused by a dysregulated host response to infection. "Regardless of the underlying mechanisms, several clinical studies have shown that ADM levels have diagnostic and prognostic value in sepsis." (PMID 40572747, 2025). "Elevated ADM levels in sepsis patients are linked to higher mortality, underscoring its clinical importance in managing critically ill patients." (PMID 39201697, 2024). "The levels of two sepsis‐associated markers (pro‐adrenomedullin and procalcitonin) were significantly higher in critical patients." (PMID 37964734, 2023). "Sepsis from various sources causes adrenomedullin release from the cells in either the small intestine or the lung." (PMID 37317092, 2023). "The primary aim of this study was to investigate the association of bioactive adrenomedullin (bio-ADM) with mortality among sepsis patients in the ED." (PMID 35482727, 2022). "Among patients with sepsis and septic shock, increased levels of adrenomedullin were associated with poor outcome and mortality." (PMID 35741064, 2022). "Plasma adrenomedullin is associated with short-term mortality and vasopressor requirement in patients admitted with sepsis." (PMID 36557054, 2022). "During sepsis, multiple processes stimulate ADM release and increased ADM levels are associated with sepsis severity, development of organ dysfunction, including vasopressor/inotrope dependency, as well as mortality." (PMID 36530868, 2022). "Several studies have reported a strong association between elevated ADM levels and mortality, severity of illness and need for organ support in sepsis patients, using either of the two methods, proposing ADM to be a predictive biomarker in sepsis." (PMID 35482727, 2022). "Adrenomedullin (ADM) is a biomarker that has been linked to endothelial dysfunction and the risk for organ failure in patients with sepsis and infection of the lung as it directly relates to the status of the endothelium." (PMID 34960714, 2021). "Previous studies have shown that circulating concentrations of both DPP3 and ADM are independently associated with the development of organ failure and adverse outcome in sepsis." (PMID 33381880, 2021). "Several studies have reported an association of increased levels of ADM and poor outcomes among patients with sepsis and septic shock." (PMID 33148300, 2020). "The strongest elevations have been observed in severe sepsis and septic shock, where increased ADM levels are associated with fatal outcome, suggesting that excessively high concentrations of ADM can be detrimental." (PMID 26266791, 2013). "Adrenomedullin (ADM), a circulating vasodilatory peptide, plays an important role in the development of sepsis-associated hemodynamic and microcirculatory disorders." (PMID 26266791, 2013). "Pro-adrenomedullin (proADM) is helpful for individual risk assessment and outcome prediction in sepsis." (PMID 16805922, 2006). "This study highlights the complex dynamics of adrenomedullin homeostasis in sepsis and suggests that early measurement of ADM-Gly and PAM activity may help refine risk stratification." (PMID 40993326, 2025). "ADM levels are linked to worsened outcomes in sepsis-related cardiac dysfunction." (PMID 39594987, 2024). "A large number of inflammatory biomarkers (C-reactive protein, presepsin, procalcitonine, proadrenomedullin, adrenomedullin, kallistatin, etc.)have been studied and were found to be associated with the presence of sepsis, with sepsis severity and sepsis outcomes." (PMID 36470834, 2022). "Serum ADM was found to be elevated in patients with sepsis and septic shock and could serve as a diagnostic and prognostic marker in septic patients." (PMID 36004964, 2022). "Bio-adrenomedullin (Bio-ADM) and Proenkephalin (PenKid) seem to have a key role in the development of organ dysfunctions induced by sepsis and, therefore, could help in the risk stratification of patients with sepsis at ED admission." (PMID 36556987, 2022).
Sepsis (continued). "As both ADM and ET-1 are potent vasoactive factors it is also plausible that they may be associated with myocardial dysfunction in sepsis." (PMID 27282767, 2016). "When sepsis proceeds to hypodynamic shock, vascular responsiveness to ADM fades, suggesting that reduced ADM function could be causal for progression of the disease." (PMID 26266791, 2013). "Therefore, impaired removal of circulating ADM during pulmonary circulation resulting from sepsis-associated lung injury may partly contribute to the elevation in plasma ADM levels." (PMID 16356231, 2005). "Sepsis severity and mortality correlated with biomarkers (procalcitonin, mid-regional pro-adrenomedullin, lactate) and clinical scores (SOFA, qSOFA)." (PMID 41898582, 2026). "Background and Objectives: Procalcitonin (PCT), presepsin (PSEP), interferon-λ3 (IFN-λ3), and bioactive adrenomedullin (bio-ADM) are promising sepsis biomarkers." (PMID 41597487, 2026). "This study provides novel insights into the dynamics of adrenomedullin (ADM) homeostasis during sepsis progression, highlighting the critical interplay between its glycine-extended precursor (ADM-Gly), fully active form (bio-ADM), and the amidating enzyme PAM." (PMID 40993326, 2025). "On the other hand, the administration of anti-ADM antibodies has also shown favorable outcomes in preclinical studies of sepsis." (PMID 40572747, 2025). "Additional genes upregulated in sepsis include adrenomedullin (ADM), IRAK3, and arachidonate 5-lipoxygenase (ALOX5/5-LOX)." (PMID 41293242, 2025). "Among several candidate biomarkers of sepsis that have emerged in recent years, this review provides existing evidence on the potential clinical utility of two novel biomarkers, adrenomedullin in its bio-active form (bio-ADM) and dipeptidyl peptidase 3 (DPP3)." (PMID 40572747, 2025). "Here, we present hourly resolved kinetics of ADM activation during early sepsis onset in a porcine model and analyze the AdrenOSS-1 human cohort data to assess biomarker changes in advanced sepsis progression." (PMID 40993326, 2025). "Pro-adrenomedullin (pro-ADM), a precursor of adrenomedullin (ADM), has been identified as a potential biomarker in various acute conditions such as sepsis, acute heart failure, cardiac arrest, and stroke." (PMID 40476215, 2025). "Previous research has shown that adrenomedullin maintains vascular tone as well as endothelial barrier function and is markedly increased during severe inflammatory disorders such as sepsis, pneumonia, and COVID-19." (PMID 41141600, 2025). "The peptide hormone adrenomedullin (ADM) plays a key role in sepsis owing to its potent vasodilatory effects, ability to maintain vascular integrity, and critical role in modulating immune responses and reducing inflammation." (PMID 40993326, 2025). "Elevated levels of ADM-Gly and PAM were also associated with increased 28-day mortality, indicating their potential as diagnostic biomarkers for sepsis." (PMID 40993326, 2025). "Another key biomarker is adrenomedullin (ADM) and its stable fragment MR-proADM, both of which serve as sensitive indicators of endothelial damage and microvascular dysfunction in sepsis." (PMID 40265185, 2025). "Adrenomedullin (ADM) is a potent hormone‐like peptide rapidly induced by hypoxia and inflammatory cytokines in the early stages of sepsis." (PMID 40387073, 2025). "The ubiquitously expressed peptide hormone adrenomedullin (ADM) has emerged as a central player in sepsis, owing to its vasodilatory properties and role in preserving endothelial barrier function." (PMID 40993326, 2025). "Second example is Adrenomedullin; its high circulating concentration correlates with mortality in sepsis and septic shock." (PMID 39003476, 2024). "A critical focus of the review was the incorporation of predictive biomarkers, such as adrenomedullin and proenkephalin, which serve as pivotal elements in the pathophysiological network of sepsis." (PMID 39594987, 2024).
Sepsis (continued). "Biomarker-guided interventions for sepsis to identify patients that would benefit more from therapy, such as sTREM-1-guided Nangibotide treatment or Adrenomedullin-guided Enibarcimab treatment, appear promising but require further evaluation." (PMID 39003476, 2024). "Research has demonstrated that ADM levels correlate with sepsis severity, organ failure, and 30-day mortality, highlighting its diagnostic and prognostic utility." (PMID 39201697, 2024). "Elevated ADM levels correlated with increased mortality in both sepsis and ICU patients, with odds ratios of 1.23 and 1.22, respectively." (PMID 39201697, 2024). "Since adrenomedullin has been described as an indicator of sepsis and organ dysfunction in bacterial and viral infections, further studies should focus on the association between DA9B and adrenomedullin." (PMID 38397016, 2024). "Adrecizumab, a monoclonal antibody that binds adrenomedullin, attenuates oxidative stress and is a drug in clinical trials as a targeted sepsis and COVID-19 therapy (NCT05156671)." (PMID 38107402, 2023). "The safety and efficacy of treatment with adrenomedullin or adrecizumab in sepsis and ARDS also need further confirmation." (PMID 36864354, 2023). "We found that high admission levels of the vasoactive peptide bio-ADM were associated with fulfilling ARDS criteria within 72 h independently of the severity of the disease as measured by SOFA and independently of sepsis status." (PMID 36864354, 2023). "Leukocytes, PCT, and ferritin were higher in sepsis, while thrombocytopenia, lymphopenia, and elevated fibrinogen and adrenomedullin (biomarker with a role for the detection of invasive infections) were more frequent in MIS-C." (PMID 37676491, 2023). "In patients with sepsis and cardiogenic shocks, recent studies showed the beneficial impact of adrecizumab, a humanized antibody directed against the N-terminus of adrenomedullin." (PMID 37109706, 2023). "The peptide adrenomedullin AM, which binds CALCRL, has been implicated in the pathogenesis of sepsis and the immune response." (PMID 37113606, 2023). "Due to its short half-life, adrenomedullin itself had little use as a biomarker; however, midregional proADM (MRproADM) is present in large quantities in the blood of sepsis patients and is stable enough to be measured clinically." (PMID 37317092, 2023). "Providing external validation to our findings, several genes, such as CD177, ARG1 (arginase), MMP9, OLAH and ADM have been described previously as having important inflammatory roles in sepsis." (PMID 38332914, 2023). "In our study, in addition to the laboratory abnormalities usually observed in these patients, we compared two other biomarkers: procalcitonin (PCT) and MR-pro adrenomedullin (ADM), two biomarkers that have previously shown utility in the diagnosis of sepsis." (PMID 37676491, 2023). "In a study enrolling 60 newborn infants with sepsis proven with positive blood cultures and 30 healthy neonates, pro-ADM serum concentrations were significantly higher (14.39 ± 0.75 nmol/L) in the sepsis group than in controls (3.12 ± 0.23 nmol/L)." (PMID 37627653, 2023). "Mid-regional pro-adrenomedullin (MR-proADM), a peptide fragment of hormone adrenomedullin (ADM), has recently emerged as a promising diagnostic biomarker in the evaluation of sepsis." (PMID 37147598, 2023). "There are genes such as Interleukin-1 receptor-associated kinase 3 (IRAK3), Adrenomedullin (ADM), and arachidonate lipoxygenase 5 (ALOX5), whose expressions were significantly upregulated in sepsis patients." (PMID 36298439, 2022). "In preclinical animal models, infusion of adrenomedullin preserved hemodynamics, reduced vascular hyperpermeability and increased sepsis survival." (PMID 35741064, 2022).